PDGFRB (platelet derived growth factor receptor beta)
Diseases named in the same sentence as PDGFRB in open-access papers (continued):
Sharing a sentence is not in itself a finding about the gene and the disease.
cancer (continued). "Further studies in HSGOC patients have shown that platelet-derived growth factor receptor beta (PDGFRβ) is essential for fibronectin-mediated clustering in malignant ascites, and that ECM production after initial detachment supports metastatic spread." (PMID 41596584, 2026). "Determining platelet-derived growth factor receptor β (PDGFRβ) expression in biological specimens is pivotal for cancer diagnosis, drug development, and therapeutic monitoring." (PMID 41884335, 2026). "CIBERSORT analysis showed that the PDGFRB expression was significantly correlated with immune infiltration in 43 cancer species, such as GBM, GBMLGG, and LGG." (PMID 40128057, 2025). "This revealed that genetic Npy1r ablation did not significantly alter the abundance of stromal cell populations or ECM including cancer-associated fibroblasts [αSMA (ACTA2) and PDGFRB; fig." (PMID 40073121, 2025). "Additional clustering and dimensionality reduction, utilizing four marker genes (ACTA2, FAP, PDGFRB, and NOTCH3), resulted in the delineation of four cancer-associated fibroblast (CAF) subpopulations." (PMID 40589759, 2025). "For paired tumors and normal tissues from the TCGA database, a total of 42 cancer samples for the PDGFRB gene were initially screened." (PMID 40128057, 2025). "The Cancer Genome Atlas (TCGA) and Genotype-Tissue Expression (GTEx) databases were utilized to analyze PDGFRB expression levels." (PMID 40128057, 2025). "Results from the TIMER database showed that PDGFRB expression was significantly correlated with immune infiltration in 37 types of cancer., including ACC, BLCA, and BRCA." (PMID 40128057, 2025). "This study presents a comprehensive pan-cancer analysis of PDGFRB, demonstrating that this gene exhibits significant differences in expression across various types of cancer." (PMID 40128057, 2025). "In 11 types of cancer, significant differences in the expression of PDGFRB were observed, particularly in UCEC, COAD, STAD, ESCA, and CHOL." (PMID 40128057, 2025). "We identified three major stromal cell types, including cancer-associated fibroblasts (CAFS; FAP, COL1A1), perivascular-like cells (PVL; PDGFRA, PDGFRB), and endothelial cells (PECAM1, CD34)." (PMID 40858992, 2025). "The prognostic significance of PDGFRB in cancer patients was assessed by analyzing 13 different types of cancer, revealing significant differences in overall survival rates." (PMID 40128057, 2025). "We found that about 84% of primary tumors expressed PDGFRβ, both in the cancer cells and surrounding supportive tissues like blood vessels." (PMID 41472102, 2025). "Overall, this study analyzes PDGFRB across various cancer types, emphasizing its prognostic and immunological significance and potential role as an immune checkpoint." (PMID 40128057, 2025). "PDGFRB was also positively associated with MHC, immune-activating genes, and immunosuppressive genes in pan-cancers." (PMID 40128057, 2025). "PDGFRB is a type III tyrosine-protein kinase that is abnormally expressed in various cancers and can serve as a biomarker for cancer prognosis, as studies have demonstrated." (PMID 40128057, 2025). "We found that four genes (EPHA3, PDGFB, PDGFRB, and GNG2) are implicated in cancer cell migration, invasion, and angiogenesis." (PMID 38233802, 2024). "The correct folding and interaction of these domains are critical for PDGFRβ′s function in signal transduction pathways, which are often dysregulated in various diseases, including cancers and vascular disorders." (PMID 39473823, 2024). "For example, APOE, PLAU, CDK1 and MUC1 were significantly higher in TNBC tissues than in cancer-parasite tissues, whereas PDGFRB, RET, ROCK2, CCND1 and PPARA were significantly lower in TNBC tissues than in cancer-parasite tissues." (PMID 38329441, 2024).
cancer (continued). "The role of cancer-associated fibroblasts (CAFs) in the immune microenvironment was acknowledged by selecting marker genes ACTA2, FAP, PDGFRB, and NOTCH321–23, aiding in dimensionality reduction for the clustering analysis, which identified five CAF clusters." (PMID 38740918, 2024). "Our results indicate that PDGFRβ exerts a pro‐adhesive function through the activation of fibronectin in cancer cells." (PMID 38010623, 2024). "In summary, the compounds Genostrychnine and Chelidonine promise a new gateway for the therapeutic development of cancers targeting PDGFRβ." (PMID 39473823, 2024). "The research on small molecule inhibitors targeting PDGFRβ in cancer treatment has seen promising developments, but significant gaps remain." (PMID 39473823, 2024). "Despite these limitations, the study provides valuable insights and a foundation for further research into potential PDGFRβ inhibitors for cancer therapeutics." (PMID 39473823, 2024). "PDGFRB is known to have proproliferative functions in cancer by signalling through the phosphatidylinositol 3 kinase (PI3K) and mitogen‐activated protein kinase (MAPK) pathways." (PMID 38877653, 2024). "PDGFRβ is a pivotal player in cancers and other diseases and acts as a promising target for therapeutic development." (PMID 39473823, 2024). "Their antineoplastic activity suggests they can inhibit cancer cell growth and proliferation, which PDGFRβ often drives." (PMID 39473823, 2024). "As expected, metastatic liver tumours, identified by the presence of CK19+ cancer cells, showed a significant expansion of PDGFRβ+ mesenchymal cells and a marked increase of CD68+ macrophages compared to healthy liver." (PMID 38678021, 2024). "Next-generation sequencing of 211 cancer-related genes was detected, and the results revealed an ETV6-NTRK3 translocation and a PDGFRB c.2632A > G mutation." (PMID 37417596, 2023). "PDGFRB was found to be overexpressed in various cancers, including lung, colon, melanoma, and breast carcinoma." (PMID 37958963, 2023). "In CRC, PDGFRβ-labeled CAFs increase the metastatic and invasive ability of cancer cells in a secreted glycoprotein stanniocalcin-1-dependent manner." (PMID 37143134, 2023). "The other subset presented the characterization of cancer-associated fibroblasts (CAFs), expressing markers such as PDPN and PDGFRB." (PMID 36646679, 2023). "Accordingly, we detected pSTAT3 staining in both fibroblasts (PDGFRβ+) and cancer cells (E-cadherin+), with a slightly bigger proportion of pSTAT3+ cells in post-NACT samples." (PMID 37400436, 2023). "Although our results show that ponatinib (PDGFRA inhibitor) is more effective than sunitinib (PDGFRB inhibitor) in reducing growth and migration of the cancer cells, both inhibitors were capable of suppressing cell proliferation and migration." (PMID 36979654, 2023). "In contrast to FbS1 in metaplastic tissues, in dysplasia or cancer regions, these cells frequently co-expressed PDGFRβ." (PMID 37196797, 2023). "PDGFRα and PDGFRβ proteins are upregulated in stromal cells of human cancers and are expressed in 10–70% of borderline or MPTs." (PMID 36522480, 2023). "We labeled cell types as endothelial cell (Endothelial, gene expression of PLVAP, KDR, PTPRB) and cancer associated fibroblasts cell (CAFs, gene expression of FAP, MMP11, PDGFRB, SFRP2, PDGFRA, ADAMTS2)." (PMID 37065499, 2023). "We found a strong pSTAT3 staining in our mIHC analysis, which was detected in both cancer cells (E-cadherin+) and stromal cells (PDGFRβ+), including CAFs (FAP+)." (PMID 37400436, 2023). "Some of the PDGFRα+ cancer-derived fibroblasts surrounding gastroids also expressed PDGFRβ, as observed in fibroblasts adjacent to epithelial cells in cancer tissues." (PMID 37196797, 2023). "Given the contribution of the positive feedback loop between PDGFRβ and histone lactylation to the pathogenesis of ccRCC, we designed a combined therapeutic approach for this cancer." (PMID 35637958, 2022).
cancer (continued). "Our data predict that the core matrisome elements within FGFR-wildtype ECM-High matreotype tumors can signal through integrins, FLT4, and PDGFRB on fibroblasts to induce pro-fibrogenic signaling that promotes cancer cell growth, migration, and invasion." (PMID 36404344, 2022). "It seems that VS1, already exhibiting genomic instability, undergoes a near whole-genome doubling as well as acquires new mutations in cancer-related genes (FOXO4, GNAQ, PDGFRB), thereby completing the malignant transformation." (PMID 34816314, 2022). "Several genes associated with cancer cell motility, including SEMA5A, PDGFRB, TGFB2, CXCR4, SNAI1, ICAM1, and NEDD9, were decreased in shGPR81 cells." (PMID 35428832, 2022). "The spontaneous malignant transformation was characterized by a near-total whole-genome doubling, disappearance of NF2 mutation and new mutations in three cancer-related genes (GNAQ, FOXO4 and PDGFRB)." (PMID 34816314, 2022). "The most abundant stromal populations of the three tumors included in the experiment were endothelial cells (PDGFRβ+), fibroblasts (CD56+ cells), and cancer-associated fibroblasts expressing αSMA and FAPα." (PMID 33670410, 2021). "For example, the transforming growth factor beta (TGFB), MAPK, ERBB, HIF-1, WNT, PDGF/PDGFRB, and NFKB signaling pathways are implicated in several aspects of cancer initiation, promotion, and progression, by mediating survival of cancer cells." (PMID 34422220, 2021). "These clinical findings, consistent with our results in mice, further confirm that BRCA1 suppresses the PDGFRβ-PKCα signaling pathway in breast basal-like cancer development and progression." (PMID 33478572, 2021). "PDGFRB, detected as being hypermethylated in stage-I BrCa, had been reported to increase proliferation and migration in several cancers, PDGFRB expression was correlated with less favorable clinicopathological parameters and shorter survival in BrCa." (PMID 33918195, 2021). "PDGFRβ has been shown as an ideal target for antagonistic therapy development in aggressive human cancers, including TNBC." (PMID 32892748, 2020). "Cancer-associated fibroblasts (CAFs) are important components of TME, and one of their surface markers is beta-type platelet-derived growth factor receptor (PDGFRβ)." (PMID 32751200, 2020). "Imatinib inhibits kinase activities of c-ABL, BCR-ABL, c-KIT, and PDGFRβ activity suppressing the proliferation of cancer cells." (PMID 32756477, 2020). "In nuclear medicine imaging, PDGFRβ has raised considerable interest as an attractive target in numerous human cancers." (PMID 33374773, 2020). "PDGFRβ is overexpressed in numerous human cancer types, including colon, breast, and pancreatic cancer." (PMID 33374773, 2020). "PDGF-D functions by binding to PDGFRβ and promoting cell growth, which increases the aggressiveness of other cancer cells, angiogenesis, and EMT of CRC." (PMID 32899998, 2020). "Historically, PDGFRβ transcript expression is well known to be activated by many stimuli to promote targeted therapy-mediated resistance in various cancers." (PMID 30777101, 2019). "In this gene-set, the cancer driver gene and drug target PDGFRB were identified on both CNV and mRNA levels." (PMID 31243065, 2019). "PDGFRβ belongs to the type III family of tyrosine kinase receptors which become dysregulated in various pathologies including cancer." (PMID 30777101, 2019). "Platelet-derived growth factor receptor beta (PDGFRβ) affects in numerous human cancers and has been recognized as a promising molecular target for cancer therapies." (PMID 29991770, 2018). "During the process of dedifferentiation, multiple genes that were demonstrated to be pivotal in cancer stem cell properties were induced, including PDGFRB, NOTCH1, JAG1, HES1, and HEY1 of the Notch signaling, SNAI1 and SNAI217–20." (PMID 29991717, 2018).
cancer (continued). "A recent work revealed that two IM-associated mutations in PDGFRB, c.1681C>T (p.R561C) and c.1998C>A (p.N666K), constitutively activate PDGFR-beta and can induce cancer development in vivo." (PMID 30200486, 2018). "To date, several types of probes targeting PDGFRβ have been developed for cancer imaging in nuclear medicine." (PMID 29991770, 2018). "This protein, PDGFRβ, is secreted by CAFs and triggers cancer growth and increased pericyte coverage of vessels, resulting in increased vessel function." (PMID 28531107, 2017). "In cancer, PDGFRβ expression is generally restricted to stromal cells of mesenchymal origin, and is absent in epithelial tumor cells." (PMID 28677655, 2017). "Our experimental results suggest that both PDGFRβ and N-cadherin are required for EMT cancer cells to associate with ECs in vitro and in vivo." (PMID 28677655, 2017). "The results support PDGFRB up-regulation as a cancer-driver mechanism and suggest this receptor as a candidate therapeutic target worth to be exploited in the treatment of this disease." (PMID 28435517, 2017). "Sunitinib is an oral small molecule tyrosine kinase inhibitor that has activity against PDGFRB, a proto-oncogene that can be activated in cancer cells." (PMID 28993730, 2017). "Due to its high affinity and specificity for PDGFRβ, affibody Z02465 and its derivative have been considered ideal tools for the delivery of anti-cancer drugs and contrast media." (PMID 29182023, 2017). "Among the identified genes, one of the most interesting was PDGFRB encoding for the platelet-derived growth factor receptor beta, already suggested as a MPM-cancer gene by previous research groups." (PMID 28435517, 2017). "The 60% of colon cancer patients express high levels of this gene and the PDGFRB expression correlates with lymphatic dissemination of this cancer." (PMID 28435517, 2017). "PDGFRβ is primarily expressed in perivascular cells and stromal fibroblasts as epithelial LLC cancer cells completely lack PDGFRβ expression." (PMID 27150562, 2016). "By then extending the collagen-based interrogation to multiple cancer types, we highlighted the potential importance of PDGFRβ as a marker in other cancers." (PMID 27128408, 2016). "Our results strongly encourage further in vivo investigation for aptamer-based approaches aimed at developing new therapeutics for GBM and other cancer types that depend on EGFRvIII and PDGFRβ for survival and growth." (PMID 26461476, 2015). "The fact that PDGFRβ is expressed in malignant tumors and that it is a transmembrane molecule and therefore easily accessible makes the protein an attractive target for the development of molecular targeting strategies for diagnosis and therapy." (PMID 22791264, 2013). "Herein, we identified highly potent PDGFRβ binders with IC50 values in an enzymatic assay below μM range with compound 5 possessing significant activity against PDGFR dependent cancer cells." (PMID 24065162, 2013). "We also show that the inhibitory properties of Triflorcas in cancer cells with RTK swapping can be partially attributed to its capacity to interfere with PDGFRβ phosphorylation." (PMID 23071625, 2012). "We therefore evaluated the inhibitory properties of Triflorcas in cancer cell lines, in which reciprocal substitution of Met, ErbBs, and PDGFRβ confers resistance to single RTK inhibition." (PMID 23071625, 2012). "Taken together, these findings support the introduction of anti-PDGFRβ antiangiogenic therapy in cancers with PDGFRβ-positive ECs." (PMID 27713269, 2010). "This study then assessed the prognostic value of PDGFRB expression in cancer patients." (PMID 40128057, 2025). "From these clusters, five major cell types were identified via classical cell markers, including T cells (CD3E, CD8A, CD3D), B cells (CD19, MS4A1, CD79A), myeloid cells (CD14, CD68, LYZ), endothelial cells (PECAM1, VWF, CDH5) and cancer-associated fibroblasts (CAFs) (ACTA2, FAP, PDGFRB)." (PMID 39941131, 2025).
cancer (continued). "Furthermore, PDGFRB showed a positive association with MHC, immune-activating genes, and immunosuppressive genes across different cancer types." (PMID 40128057, 2025). "Moreover, chimeric spheroids conformed by CAFs and sh‐PDGFRB cells did present cancer cells as well, increasing the number and diameter of those of sh‐PDGFRB, recovering sh‐CTRL spheroids phenotype." (PMID 38010623, 2024). "Moreover, GEPIA analysis of TCGA data showed that PDGFB and PDGFRB were significantly overexpressed in various types of human cancers." (PMID 37307823, 2024). "PDGFRB abnormalities have been reported in some cancers such as colorectal cancer (CRC)." (PMID 39678505, 2024). "Besides imatinib, crenolanib is another TKI that is capable of inhibiting PDGFRB and has shown promising results in lung cancer and colon cancer cell lines." (PMID 37958963, 2023). "The fibroblast marker PDGFRB was mainly expressed in cancer-associated fibroblasts in OV (data not shown)." (PMID 37658364, 2023). "In the in vivo studies, combination therapy using an inhibitor of miRNA-1246 and paclitaxel led to the significant inhibition of tumor growth, which was associated with reduced proliferation of cancer cells, downregulation of PDGFRβ, and upregulation of Cav1 in cancer tissue." (PMID 37736898, 2023). "Furthermore, we exprlored the expression of marker genes (PDPN, THY1, PDGFRB, PDGFRA,and POSTN) for cancer-associated fibroblasts (CAFs) in different cell types, and found that all marker genes were highly expressed in fibroblasts." (PMID 36973787, 2023). "This suggests a significant function of PDGFRA and PDGFRB in S:E fusion-positive cancer." (PMID 36579559, 2022). "Interestingly, P-Rex1/Rac1 is known to cooperate with PDGFRβ in cancer cell invasion, which, along with neointimal hyperplasia, are classical examples of dysregulated cellular migration." (PMID 35241778, 2022). "Previous study has disclosed PDGFRB as a gene involved in cancer progression." (PMID 33731124, 2021). "Importantly, this group of fibroblast cells expressed the markers for cancer‐associated fibroblasts (CAFs) including ACTA2 (encoding α‐SMA), PDGFRA, PDGFRB, DDR2, FAP, and CAV1." (PMID 34459128, 2021). "Notably, four of these proteins (i.e., EGFR, IGF-IR, PDGFRβ and Axl) also showed the highest increase in phosphorylation in cancer tissue samples after denosumab treatment compared to untreated samples." (PMID 34298757, 2021). "Because of this, PDGFRβ is one of the targets for cancer treatment and therapy." (PMID 33374773, 2020). "Moreover, immunohistochemistry analysis of lung metastasis nodules revealed the increased expression of two cancer‐associated fibroblast (CAF) markers CD44 and PDGFRβ, in vec‐sEVs pre‐conditioning lung metastasis nodules." (PMID 33304474, 2020). "Moreover, the Platelet Derived Growth Factor Receptor Beta (PDGFRb) is essential for cellular growth, proliferation, survival, motility and differentiation and is overexpressed in cancer." (PMID 33255335, 2020). "In addition, histological staining of the cancer samples revealed that most of the PDGFRβ expressing cells were localized in the vimentin-positive periepithelial stroma." (PMID 31690270, 2019). "(B) Heatmap analysis of correlation of PDGFRβ with JAK2 levels in pan-TCGA cancer samples." (PMID 30777101, 2019). "Among these candidate genes, PDGFRB is the most studied gene related to cancer." (PMID 29740513, 2018). "EMT markedly activates the expression of both PDGFRβ and N-cadherin in cancer cells." (PMID 28677655, 2017). "Moreover, we showed, in TCGA network of variant cancers and the ovarian microdissected profile, that SNAI2 was positively related with classical CAF activation markers, such as ACTA2, FAP, and PDGFRB." (PMID 29041931, 2017). "Interestingly, expression of PDGFRB in carcinomas is generally restricted to stromal cells of mesenchymal origin and is generally absent in epithelial tumour cells." (PMID 28978141, 2017).